IL6 (interleukin 6)
Diseases named in the same sentence as IL6 in open-access papers (continued):
Sharing a sentence is not in itself a finding about the gene and the disease.
Sepsis (continued). "The results of this study suggest that IL-6 is better than PCT and CRP in predicting the treatment success in predominantly non-surgical sepsis in the first 48–72 h." (PMID 30760225, 2019). "Sepsis, but not PAB, led to increase in endothelial damage marker PAI-1 and cytokines TNF and IL-6 (all p<0.05) in plasma." (PMID 31247004, 2019). "The laboratory indicators used for the clinical diagnosis of sepsis include CRP, IL-6, IL-8, tumor necrosis factor-α (TNF-α) and PCT, none of which are ideal diagnostic indicators due to their deficiencies in diagnostic specificity and sensitivity." (PMID 29760745, 2018). "The serum concentration of sTREM-1, but not IL-6 or IL-8, also predicted the ICU mortality and 28-day mortality in cancer patients with severe sepsis and septic shock." (PMID 29282483, 2018). "We found that TSH radically attenuated the release of IL-6, CXCL-1 and MCP-1 in the secondary CLP-induced sepsis but TH alone did not." (PMID 30291296, 2018). "Previously proposed markers for the differentiation of non-infectious SIRS and sepsis in adults like CRP, IL-6, and PCT performed only slightly better than chance and considerably worse than the model developed in the RF approach, when applied to our data." (PMID 29544449, 2018). "In line, kisspeptin levels did not correlate with established sepsis-markers routinely assessed in critically ill patients such as C-reactive protein (CRP), procalcitonin (PCT) and interleukin-6 (IL-6)." (PMID 30332461, 2018). "Some of the identified variables like PCT, CRP and IL-6 have been proposed before as markers for the differentiation between non-infectious SIRS and sepsis; others have not yet been described." (PMID 29544449, 2018). "In PBMCs and monocytes from sepsis patients, CDDO-Me(bardoxolone methyl) treatment did not reduce LPS-induced Il-6 transcript accumulation although there was target engagement as measured by elevated expression of Nqo-1." (PMID 28886135, 2017). "Thrombocytopenic mice are associated with a higher systemic bacterial load, increased plasma levels of pro-inflammatory cytokines (TNFα, IL-6, and IFN-γ) and accordingly a poorer outcome of sepsis induced by Gram-negative bacteria." (PMID 28428949, 2017). "While levels IL-8, IL-6, CRP, and PCT increased in sepsis compared to non-infective SIRS, only IL-6 positively correlated with sepsis severity." (PMID 29459855, 2017). "Sepsis induced an increase in pro-inflammatory cytokines (TNF-α and IL-6) into the kidney, but there was no statistical difference between the LPS + FR and LPS + BT groups." (PMID 27993148, 2016). "Sepsis biomarkers, including PCT, IL-6 or CRP, did not help to explain discordant test results for BC and SF." (PMID 26986826, 2016). "Pro-inflammatory mediators, including IL-1ß, IL-6 and VEGF can induce MDSC, and it was notable that interphase neutrophils correlated with plasma IL-6 concentrations, but not plasma VEGF concentrations in sepsis." (PMID 25084831, 2014). "Although plasma NGAL and IL-6 were increased by sepsis, urinary TIMP-2 and NAG were increased not by sepsis, but by the presence of severe AKI." (PMID 25524453, 2014). "Our observation that hMSCs can suppress IL-2, IL-6 and TNF but not IFNγ is consistent with a previous finding in which administration of mMSCs reduced serum levels of IL-6 and TNF but not that of IFNγ in a cecal ligation and puncture model of sepsis." (PMID 24423010, 2014). "Cytokine levels TNF, IL-6 and IL-10 were highest in CAP (82%) with fatal severe sepsis and lowest in CAP with no severe sepsis." (PMID 24363503, 2013). "Procalcitonin and IL6 also performed well as markers of sepsis whilst in this intensive care unit (ICU) population, HBP did not: PCT 0.840 (0.778 to 0.901), IL6 0.805 (0.739 to 0.870) and HBP 0.607 (0.519 to 0.694)." (PMID 23531337, 2013).
Sepsis (continued). "We examined two potential to biomarkers to identify AKI: urine IL-6 and urine NGAL, Urine IL-6 and urine NGAL both increased in sepsis-induced AKI; however, the levels did not correlate well with GFR." (PMID 24265742, 2013). "On admission, neonates with sepsis (uncertain sepsis, clinical sepsis, and positive blood culture sepsis) had a significantly higher WBC count, and serum levels of IL-6, PCT, and hs-CRP than those neonates without sepsis (p< 0.01)." (PMID 22708043, 2012). "Our results showed that WBC, IL-6, hs-CRP, and PCT values were higher among neonates with sepsis compared with those without sepsis either at the time of admission or at the end of the first day of life." (PMID 22708043, 2012). "The differences were not equal: median CRP and LBP levels in sepsis were about 1.5 to 2 times higher in sepsis, whereas median PCT and IL-6 were about 10 times higher in sepsis as compared to SIRS." (PMID 21687569, 2011). "Previously, it was demonstrated that delirium is associated with elevated levels of IL-6, IL-8, and S100-β in non-ICU patients and with IL-6 and S100-β in ICU patients with sepsis." (PMID 22206727, 2011). "Both models of sepsis markedly increased plasma levels of TNF-α and IL-6, without statistically significant intergroup differences." (PMID 22030145, 2011). "IL-6 levels did not specifically correlate with SOFA and MOD scores of the sepsis group, pointing to sFas as a marker for sepsis and clinical outcome." (PMID 21232130, 2011). "The main aim of this study was to compare the levels of HMGB1, LBP, IL-6 and CRP between infected children without systemic inflammatory response syndrome (SIRS) and children with sepsis of different severity levels." (PMID 20158885, 2010). "In particular, IL-6 and CRP are known to be relatively non-specific biomarkers, compared with more validated biomarkers for sepsis, such as procalcitonin and triggering receptors expressed on myeloid cell (TREM)-1." (PMID 20202204, 2010). "CRP, leptin, IL-6 and TNF-α were compared among the following groups: sepsis group (n = 40), SIRS group (n = 34) and non-SIRS group (n = 32)." (PMID 20230641, 2010). "The levels of LBP, IL-6 and CRP were statistically significantly higher among patients with sepsis compared to those infected but without SIRS (p < 0.001)." (PMID 20158885, 2010). "Overall these results match those of other studies analyzing the levels of IL6 in infected patients without SIRS and sepsis in surgery patients, neonatal age patients, children with acute apendicitis." (PMID 20158885, 2010). "Levels of HMGB1, LBP, IL-6 and CRP in infected children without SIRS, with sepsis and with severe sepsis." (PMID 20158885, 2010). "When dividing the severe sepsis patients in surviving (n = 91) and non-surviving patients (n = 78), mean SOFA score, as well as IL-6 plasma levels were significantly higher in non-surviving patients compared to survivors." (PMID 19941661, 2009). "Attime of diagnosis, serum IL-1β, IL-6, IL-8, and TNF-α levels of culture-provensepsis and culture-negative sepsis were significantly higher than levels atseventh day after antibiotic treatment (P<.05)." (PMID 18274637, 2007). "At the time of diagnosis, IL-1β, IL-6, IL-8, and TNF-α levels of culture-proven sepsis and culture-negative sepsis were significantly higher than levels at the seventh day after antibiotic treatment." (PMID 18274637, 2007). "In our study PCT performed poorer than CRP, IL-6 and LBP in diagnosing infection and in discriminating between noninfectious SIRS and sepsis/severe sepsis." (PMID 16569262, 2006). "In the CLP-induced sepsis model, pathological browning of WAT in non-obese mice is triggered via multiple pathways: sepsis-induced inflammatory factors (TNF-α, IL-6) drive M2 macrophage polarization, and the catecholamines secreted by M2 macrophages activate β-3ARs on adipocytes." (PMID 41498391, 2026).
Sepsis (continued). "Additionally, THCQ appears to affect levels of WBC, PCT, CRP, IL-6, SAA, and PLT, with no severe adverse events observed, providing a valuable strategy for the treatment of sepsis." (PMID 40963685, 2025). "This tug-of-war involves not just IL-6, but a chorus of markers, like tumor necrosis factor-alpha (TNF-α), which kickstarts the cytokine storm, and C-reactive protein (CRP), a downstream signal of inflammation, all shaping sepsis’s chaotic course." (PMID 40149943, 2025). "Interestingly, LGG attenuated all parameters (mortality, Scr, ALT, SHIRPA, and cytokines) in non-aging sepsis (PBS-CLP) while improving all these parameters, except for mortality and serum IL-6, in aging sepsis (D-gal CLP)." (PMID 39423218, 2024). "Amphiregulin was the only analyte which could distinguish Sepsis samples with low or normal CRP from No-Sepsis samples, whereas amphiregulin, IL-6 and IL-10 could all distinguish No-Sepsis samples from Sepsis samples where CRP was elevated." (PMID 38195661, 2024). "Univariate analysis found 15 risk factors showed differences between ARDS and non-ARDS, namely, interleukin 6, interleukin 8 (IL-8), angiopoietin II, LIPS, APACHEII, SOFA, PaO2/FiO2, age, sex, shock, sepsis, acute abdomen, pulmonary contusion, pneumonia, hepatic dysfunction." (PMID 39319361, 2024). "Meloxicam treatment in low IL-6 responders septic mice decreased PLF PGE2 (119.22-fold, adj.P=0.01) levels compared to Non-A sepsis groups, while circulating PGE2 increased in the Metamizole treated low IL-6 responders septic group compared to Meloxicam-treated mice (1.11-fold, adj.P=0.017)." (PMID 39281680, 2024). "In a randomized, double-blind, interventional clinical trial in critically ill children with sepsis or surgery, glutamine supplementation maintained HSP70 levels for longer but did not increase glutamine levels and did not influence IL-10 or IL-6 levels and outcome." (PMID 36615909, 2023). "During sepsis (resulting from severe infection mostly with Gram-negative bacteria), platelets become overactivated and release PEVs containing numerous molecules and DAMPs, such as HMGB1, proinflammatory cytokines (IL-1β, TNF-α, IL-6) and chemokines (MCP-1)." (PMID 37559007, 2023). "Interestingly, we found that carvacrol prevents elevations in the levels of the inflammatory cytokines IL-6 not TNF-α in serum and peritoneal lavage and protects organs from damage in a murine model of LPS-induced sepsis." (PMID 37550359, 2023). "While the introduction of SOFA scores has helped to standardize the clinical management of sepsis, existing sepsis markers, such as CRP, PCT, and IL-6, may not always accurately predict patient outcomes." (PMID 37510189, 2023). "Our previous multicenter study indicated that the level of IL-6 was decreased in the CRRT group compared with the non-CRRT group, and CRRT decreases hospital mortality rate in pediatric severe sepsis, especially in patients with acute respiratory distress syndrome (ARDS)." (PMID 36650427, 2023). "Finally, omentin-1 at sepsis onset presented a significant positive correlation only with CRP, but not with procalcitonin, IL-1β, IL-6, IL-10, or suPAR." (PMID 37241065, 2023). "However, the sensitivity and specificity of the main laboratory indexes for clinical diagnosis of sepsis are not satisfactory, including C-reactive protein (CRP), interleukin-6 (IL-6), and procalcitonin (PCT)." (PMID 36199375, 2022). "In another study of a small cohort of sepsis, severe sepsis and shock patient admitted to ICU, the levels of IL-6, IL-8 and IL-18 resulted higher in non-survivors compared to survivors, although following multivariable logistic regression analysis only IL-18 remained related to mortality." (PMID 36189302, 2022).
Sepsis (continued). "PCT levels were not connected with IL-6, IL-12, or SOFA ratings in the sepsis group [r = 0.149, P = 0.176; r =−0.141, P = 0.202; r = 0.163, P = 0.138], but were positively correlated with WBC, CRP, and IL-8 [r = 0.430, P < 0.001; r = 0.285, P = 0.009; r = 0.258, P = 0.018]." (PMID 35937269, 2022). "Thus, as sepsis biomarkers, HBP and MPO were not as prone as IL-6 and IL-8 to the effect of sample timing." (PMID 33461369, 2021). "However, children with sepsis had higher levels of HBP, CRP, IL-6, PCT, N%, and D-dimer than children without sepsis." (PMID 34778149, 2021). "The results of the present study were consistent with previous reports, in that IL-6, IL-8, MCP-1, G-CSF, IFN-γ, and TNF-α were higher than in healthy subjects, but IL-18 and IL-17A were not significantly different between healthy subjects and sepsis patients." (PMID 34654467, 2021). "Furthermore, some inflammatory markers were higher in the septic shock group compared to the sepsis group including PCT (2.6 [0.4–34.2] vs. 18.8 [7.0–66.5], p = 0.011), and IL-6 (309 vs. 658, p = 0.027), but not WBC or CRP." (PMID 35071235, 2021). "Serum samples of sepsis patients (as compared to non-septic patients) contained higher neutrophil counts (13.3 × 109 vs. 6.5 × 109 cells/l) and higher concentrations of MPO (13.1 vs. 8.8 ng protein/mL), IL-6 (188 vs. 23 pg/mL), and TNFα (348 vs. 63 pg/mL)." (PMID 32050431, 2020). "We could not definitely differentiate sepsis vs KICS because blood cultures, KSHV viral loads, and IL-6 levels were not assessed during admission." (PMID 32991474, 2020). "Although IL-6, IL-8, KC-like, and RANTES acted as inflammatory mediators in our population of septic cats, they had no prognostic value, and they were not reflective of sepsis severity." (PMID 32548135, 2020). "In vitro a significant reduction for IL-6, IFN-y, MIP-1α, C5a, HMGB-1, procalcitonin and S100-A8, but not of TNF-α could be achieved in blood samples with sepsis-like high cytokine levels by binding to CytoSorb® hemoadsorbent polystyrene beads." (PMID 33141843, 2020). "Similarly, significant differences in IL-6, IL-8, and PCT were demonstrated when comparing children with appendicitis and those with nonappendicitis sepsis." (PMID 30918467, 2019). "Additionally, several other diagnostic and prognostic biomarkers have been identified in sepsis, such as CRP, serum lactate, and IL-6, but the sensitivity or specificity is not high enough for enhancing the timely intervention of sepsis." (PMID 31771650, 2019). "To determine whether GSS inhibits sepsis-induced inflammatory response and ALI via lung vascular ECs, we further check the expression and secretion changes of TNF-α and IL-6 in ECs with and without LPS stimulation." (PMID 32082076, 2019). "Additionally, in sepsis, high negative correlations between liver CYP3A11 expression and serum IL-6, but not BUN, were demonstrated (r2=0.4650)." (PMID 30991873, 2019). "Trauma or burn injury prior to death may increase IL-6 levels, and therefore the measurement of at least two postmortem CRP values seems to be warranted in order to identify sepsis-related fatalities when no anamnesis is available." (PMID 31661804, 2019). "Although studies reported that the levels of IL-6 and TNF-α decreased with time, there is currently no consensus to guide clinicians in terms of controlling the levels of inflammation and DAMPs in AKI patients with sepsis managed through CRRT." (PMID 30666251, 2018). "TNF mediates inflammation in a classic “sepsis” cascade in tissues—in this pathway LPS from gram negative bacteria activates TNF release from cells, and then TNF stimulates production of IL-1b, IL-6, and IL-8, leading to neutrophil attraction into sites of infection." (PMID 30828428, 2018). "However, in the lipopolysaccharide (LPS) model of sepsis, while overexpression of PPAR-γ in cardiomyocyte prevents septic cardiac dysfunction, cardiac mRNA levels of interleukin 1β (IL-1β), IL-6, and TNF-α are not reduced." (PMID 28845215, 2017).
Sepsis (continued). "In an animal model of sepsis, resuscitation of septic animals with Saline resulted in not only higher incidence of AKI and greater severity of AKI but also higher inflammatory mediator concentrations (IL-6) when compared to Plasma-Lyte." (PMID 27716310, 2016). "In patients with sepsis, we observed a strong positive correlation of chemerin with blood leucocyte count (p = 0.02) and thrombocyte count (p = 0.03), but not with C-reactive protein (CRP), interleukin-6 or glomerular filtration rate." (PMID 26873079, 2016). "IL-6, CRP and TNF-α are common and sensitive but non-specific markers of inflammatory processes and increased concentrations are measured after trauma and in sepsis." (PMID 25609264, 2015). "Also, at the time of diagnosis, IL-1beta, IL-6, IL-8, and TNF-alpha levels of culture-proven sepsis and culture-negative sepsis were significantly higher than levels at the seventh day after antibiotic treatment." (PMID 23869218, 2013). "Since inflammatory markers with early kinetics such as IL-8 or IL-6 are not yet routinely available at our institution, we have now adopted a protocol that measures initial CRP values during rule-out of early onset sepsis during routine laboratory tests at 12 hours of age." (PMID 24244325, 2013). "However, there were not any significant correlation between serum levels of IL-6 and PCT in patients with clinical sepsis (r=0.03, p=0.5) and positive blood culture sepsis (r=0.07, p=0.65)." (PMID 22708043, 2012). "When incubated for 6 hours without extrinsic stimuli, whole blood from sepsis patients, which already contained greater inflammatory cytokine concentrations than that of healthy volunteers, showed a significant further increase of supernatant TNF, IL-6, IL-8, IL-1α, and IL-1β concentrations." (PMID 37869001, 2023). "As such, there was an enhanced severity of sepsis in macrophage-depleted mice with CLP compared with CLP in the Lipo group, as indicated by the survival analysis, leaky gut, serum cytokines (TNF-α and IL-10, but not IL-6), serum creatinine, and alanine transaminase." (PMID 38132765, 2023). "Another limitation of this study was the lack of Pct or IL-6 measurements, as both of them increase early, within 2 h and 2–4 h, respectively, after sepsis initiation, and IL-6 has been found to be positively correlated with YKL-40 levels in patients with sepsis." (PMID 37238320, 2023). "Given the ongoing development of therapeutics that target trans-specific IL-6 signalling and therapeutics that target CRP itself, this may represent a future avenue in sepsis therapeutics; however, this does not alter the interpretation of the primary IL6R blockade-related finding here." (PMID 36716318, 2023). "Therefore, the immunotherapeutic strategies of sepsis in the past were mainly to inhibit the inflammatory response and block the pro-inflammatory cytokines such as PAMPs, Toll-like cytokines (TLRs), TNF-α, IL-6, etc., but the results were not as expected." (PMID 37292207, 2023). "In all selected sepsis patients, regardless of AGI status, the FC value was positively correlated with D-lactic acid, IL-6, and SOFA and APACHE II scores (P < 0.05); D-lactic acid was positively correlated with IL-6, SOFA and APACHE II scores in the AGI group (P < 0.05)." (PMID 35047957, 2021). "Indeed, CRP and IL-6 levels both substantially differ between non-septic and septic patients, as well as between septic patients and patients with SIRS, thereby allowing for no sepsis, sepsis and SIRS to be differentiated." (PMID 32912236, 2020). "In mice subjected to CLP and fed a HFD, but not treated with Candida, sepsis were more severe than regular diet mice as determined by survival, organ injury (serum creatinine and alanine transaminase), serum cytokines (TNF-α and IL-6), gut leakage by FITC–dextran and endotoxemia, but not serum BG." (PMID 33101279, 2020).